RNU6-754P (RNA, U6 small nuclear 754, pseudogene)
Gene: Small nuclear RNA gene on chromosome 6 (46,018,745 to 46,018,851, forward strand). Ensembl gene ENSG00000212468.
Homologues: Orthologues: chimpanzee U6 (97% identical), macaque U6 (93% identical), dog RNU6-754P (83% identical), pig U6 (73% identical), mouse Gm24527 (70% identical), rat LOC120096754 (64% identical). Paralogues in human: RNU6-820P (81% identical), RNU6-1152P (79% identical), RNU6-166P (79% identical), RNU6-41P (79% identical), RNU6-1060P (79% identical), RNU6-15P (79% identical), RNU6-44P (79% identical), RNU6-509P (79% identical), RNU6-589P (79% identical), RNU6-73P (79% identical), RNU6-1019P (78% identical), RNU6-1035P (78% identical), and 1288 more.